PIK3CA (phosphatidylinositol-4,5-bisphosphate 3-kinase catalytic subunit alpha)
Diseases named in the same sentence as PIK3CA in open-access papers (continued):
Sharing a sentence is not in itself a finding about the gene and the disease.
tumor (continued). "Similarly, in the BELLE-2 randomised clinical trial assessing response to buparlisib in previously treated HR+/HER2- locally advanced or metastatic breast cancer patients, longer PFS was detected specifically in patients where PIK3CA mutations were detected in circulating tumour DNA (ctDNA)." (PMID 39322687, 2024). "Another study comparing PIK3CA mutations in CTCs and primary tumors, revealed that CTCs can exhibit heterogeneity within a single patient, and may acquire additional genomic characteristics that differ from those of the primary tumor." (PMID 39711963, 2024). "Moreover, the effects of specific combinations of multi‐PIK3CA mutations on clinical tumor responses remain unclear." (PMID 39054873, 2024). "PIK3CA mutations may be associated with poor prognosis and tumor recurrence in TNBC." (PMID 38857504, 2024). "Nevertheless, it remains uncertain whether these patients have an insufficient adaptive immune response or, more likely, alterations within HNSCC with HPV integration (such as TRAF3 and PIK3CA mutations) facilitate the evasion of tumour cells from the immune system." (PMID 38643337, 2024). "Similarly, in another study, CRC patients with concomitant mutations of KRAS and PIK3CA lead to poor clinicopathological parameters, including the location of the tumor at the proximal colon, the poorly differentiated state of the tumor, and significantly elevated levels of CA-199 and CA125." (PMID 39056802, 2024). "Notably, chest wall metastasis often carried enrichments of PIK3CA mutations, which have been previously speculated to promote tumor malignancy and treatment resistance." (PMID 39334392, 2024). "Furthermore, we sought to investigate the co‐occurrence of multi‐PIK3CA mutations with other genomic alterations, postulating that these combinations may influence tumor behavior and treatment responses." (PMID 39054873, 2024). "Thus, PIK3CA mutation AF in the liquid biopsy had a stronger correlation with tumor burden." (PMID 37344660, 2023). "In addition, we previously reported a significant relationship between PIK3CA mutations and lower pCR rate (adjusted p= 0.024) among 425 cancer‐related genes assessed by next‐generation sequencing of archived tumor blocks from 50 patients enrolled in this clinical trial." (PMID 38077249, 2023). "Indeed, PIK3CA mutation was found in 83% of the metastatic tumor tissue." (PMID 37047814, 2023). "Furthermore, WNT/β-catenin pathway-mediated PIK3CA mutations may reduce the sensitivity of tumor cells to the dual PI3K/mTOR inhibitor." (PMID 37046703, 2023). "However, because these studies may incorporate patients with a wide range of tumor burden, parsing out the factor of tumor burden may provide insights to our understanding of the clinical impact of PIK3CA mutation." (PMID 37344660, 2023). "Moreover, ctDNA analysis can identify tumor alterations that may help in treatment choice, both as predictor of response mutations (e.g., PIK3CA mutations for PIK3CA-inhibitors) and resistance (e.g., ESR1 mutations)." (PMID 37225714, 2023). "This tumor-like vascular transformation seems to occur only under specific conditions and may be triggered in vivo by additional somatic gain-of-function mutations in PIK3CA which can act as a “vascular oncogene”." (PMID 35661927, 2022).
tumor (continued). "In contrast to the induction of Pik3ca mutation in adulthood, these prenatally induced animals were followed without incident for up to 1 year, when one male mutant rapidly developed an unpigmented, circumscribed tail tumor of 5 mm in diameter and showed signs of distress." (PMID 36353506, 2022). "In addition, there was a higher rate of PIK3CA mutation in the high-risk subgroup compared with the low-risk subgroup, which could mean that tumor growth in high-risk BRCA cases is promoted through the PI3K–AKT signaling pathway." (PMID 35646057, 2022). "As BRAF and PIK3CA mutations tended to co-occur in the ATC tumours, we hypothesized that the introduction of a PIK3CA mutation into a BRAF mutant PTC model would lead to increased aggressiveness and cellular dedifferentiation, mimicking a possible route of progression from PTC to ATC." (PMID 35193694, 2022). "In addition, in 48B-originating tumor cells a unique mutation was found in PIK3CA, and RET genes." (PMID 36291930, 2022). "Moreover, PIK3CA mutations are closely related to tumor metastasis." (PMID 35277182, 2022). "However, this prognostic impact varied according to the tumor PIK3CA mutational status." (PMID 33673133, 2021). "Notably, PIK3CA mutations are more frequently detected in metastases than in the primary tumor." (PMID 33807876, 2021). "However, intratumor heterogeneity of PIK3CA mutations was observed in three of the eight cases in which multisampling of the tumor was performed, and only one case showed both PIK3CA mutation in the eutopic endometrial glandular epithelium and homogeneous PIK3CA mutation in the tumor." (PMID 34172890, 2021). "Indeed, some scientists advised that the reduced expression of the tumour suppressor PTEN may diminish PI3K signalling through reducing negative regulation on the p110 subunit encoded by the PIK3CA gene." (PMID 34884690, 2021). "Therefore, targeting the PI3K or MAPK signalling pathways could potentially represent an improved treatment strategy and help to improve trastuzumab sensitivity, particularly in tumours harbouring PIK3CA and/or ERBB-family mutations." (PMID 33933113, 2021). "In this clinical setting, the Eve/Exe combination and fulvestrant monotherapy remain two valid treatment options for patients with PIK3CA-wt neoplasms, while patients with PIK3CA-mutated neoplasms could potentially benefit from either fulvestrant/Alp or Eve/Exe." (PMID 32252811, 2020). "Moreover, we cannot exclude that tumour heterogeneity lowered the mutated allele frequencies of the reference mutations, particularly in PIK3CA, and thus could have resulted in a false interpretation of CTNNB1 mutational homozygosity." (PMID 33115416, 2020). "Thus, it could be reasonable to conclude that adding BYL719 with abemaciclib leads to durable anti-tumor effects in some tumor types with PIK3CA mutations." (PMID 32899250, 2020). "However, relative abundance of a fraction of cells harboring PIK3CA (H665D) and mTOR (V1795M) mutations, which are predicted as likely functional mutations, declined substantially in the lung metastasis compared to the primary tumor." (PMID 31953485, 2020). "The failure of Pik3caH1047R alone to induce tumours in this model (and also in the knock in models of Robinson and Berenjeno) is different from the transgenic mouse models driven by exogenous promoters, where Pik3ca mutation alone was able to induce lung, breast and colon tumours." (PMID 31018529, 2019). "Thus, it is unclear whether MAP3K1 alterations are causal to enhanced sensitivity to PIK3CA antagonists, or if they instead mark a specific tumor phenotype." (PMID 31552290, 2019). "However, following treatment, PIK3CA mutation may be enriched in HER2-amplified tumor cells (e.g., as a resistance mechanism to HER2-targeted therapy)." (PMID 31146717, 2019).
tumor (continued). "As hypothesized above, the genetic composition of the tumor may change from the first-line to later-line setting and affect the impact of the PIK3CA mutation on outcome in different disease settings, as observed between the MARIANNE, EMILIA and TH3RESA studies." (PMID 31146717, 2019). "However, the inclusion of the preselected samples might account for the high overall observed frequency of PIK3CA mutations in tumor tissue compared to the unselected samples (24%; 11/46)." (PMID 29689598, 2018). "Additionally, recent results of a large-scale profiling study in GC confirmed a high grade of tumor heterogeneity in EBV-positivity and PIK3CA mutations, suggesting caution in the extrapolation of tumor genomic profiling from the analyses of single tissue biopsies." (PMID 30008616, 2018). "In addition, our patient tumor sample was positive for a PIK3CA mutation." (PMID 28903344, 2017). "Interestingly, the expression of H1047R (one of the most frequent mutations of PIK3CA) in lineage-committed basal or luminal cells of the adult mouse mammary gland evokes cell dedifferentiation into a multipotent state that contributes to tumor heterogeneity." (PMID 28894288, 2017). "We evaluated the significance of RAS/PIK3CA/BRAF tumor mutations in patients receiving combination chemotherapy with Bmab as the first-line treatment for mCRC, and we assessed whether these mutations could be used to select patients who would derive the greatest clinical benefit from Bmab." (PMID 28068936, 2017). "Also in the MSI tumor investigated in our study, PIK3CA was mutated by a somatic SNV." (PMID 28683819, 2017). "Abnormal activation and amplification of the PIK3CA oncogene—encoding the catalytic subunit of PI3Kα—is one of the most commonly observed events associated with malignant transformation and found to be present in multiple tumor types including breast, colon, and ovarian cancer." (PMID 28273837, 2017). "Several adjunctive variables, not investigated in the present study, such as the level of stromal Lymphocyte Tumor Infiltration (sTIL) and PIK3CA mutations, EGFR or PTEN expression, along with distinct intrinsic molecularly-defined subtypes, may have influenced outcomes." (PMID 26910921, 2016). "However the impact of PIK3CA mutations on prognosis varies among tumor types." (PMID 27388016, 2016). "Despite the well-established differences in PTEN loss and PIK3CA activation, these mutations behave similarly in their response to the two-step therapy, suggesting that tumours carrying either PTEN loss or oncogenic mutations in PIK3CA could benefit from the two-step therapy." (PMID 27897178, 2016). "Additionally, the presence of highly viscous mucinous secretions by various adenocarinomas and neoplasms could potentially be explained by alterations in PTEN or point mutations resulting in a gain of function within PIK3CA." (PMID 27073869, 2016). "For example, a recent study demonstrated that the frequent presence of subclonal driver mutations, such as E545K PIK3CA, may necessitate the stratification of targeted therapy response according to the percentage of tumour cells in which the driver is identified." (PMID 26117819, 2015). "Since we had been able to confirm the hypothetical molecular mechanisms underlying the PFR-drug associations between AEW541 and PIK3CA in tumor samples, we wondered whether we could also predict survival of actual cancer patients using the PFRs identified in the CCLE data." (PMID 25568936, 2015). "Of the 15 PIK3CA mutations detected in tumours by droplet digital PCR, 14 of the corresponding ctDNA mutations were detected in presurgical plasma, whereas no mutations were found in plasma from patients with PIK3CA wild-type tumours (sensitivity 93.3%, specificity 100%)." (PMID 26101870, 2015).
tumor (continued). "Altogether, these results indicate that aberrant signalling through the PI3K pathway – induced by mutant Akt1, PIK3CA or by PTEN loss - significantly increases the percentage of cells able to initiate in vitro growth as spheroids enriched in TICs that efficiently support tumor growth in vivo." (PMID 26486080, 2015). "Interestingly, PIK3CA mutations are associated with K-Ras mutations in advanced tumours, which may result in constitutively active Cdc42 in these cells." (PMID 27919038, 2014). "Because the binding of insulin to its receptors activates the PI3K/AKT/mammalian target of rapamycin (mTOR) signaling cascade, activating mutations in the PIK3CA oncogene may determine tumor response to DR-like pharmacological strategies targeting the insulin and mTOR pathways." (PMID 23986086, 2013). "PIK3CA mutation is an emerging tumor marker which might become used in treatment-choosing process." (PMID 22330809, 2012). "Taken together, this study illustrates that Trastuzumab can induce regression in a HER-2 positive tumor, and that PIK3CA mutation (in a HER-2 positive background) may be a potential resistance mechanism to Trastuzumab treatment in pre-clinical patient-derived EC xenograft models." (PMID 22935382, 2012). "Our studies show that the effects caused by abrogation of PIK3R1 and PIK3CA result from different signaling mechanisms in individual cell lines, likely reflecting different signaling mechanisms in the individual tumors (and perhaps in individual cells of the same tumor)." (PMID 22064833, 2011). "Thus further knowledge about tumor-related mutations in PIK3CA might be gained by comparing those variants to orthologs in other species as well as paralogs of related kinases." (PMID 21208444, 2011). "In addition, incorporating biomarker (PIK3CA mutation, Ki67 tumor cell proliferation and cell death markers) analysis in early-phase PI3K inhibitor trials may aid in identifying patients most likely to benefit from these therapeutic agents." (PMID 21362200, 2011). "Tumor tissues from 504 patients with diverse cancers referred to the Clinical Center for Targeted Therapy at MD Anderson Cancer Center starting in October 2008 were analyzed for PIK3CA, RAS (KRAS, NRAS), and BRAF mutations using polymerase chain reaction-based DNA sequencing." (PMID 21829508, 2011). "Together, our results demonstrate that PIK3CA mutations in PROS profoundly remodel the tissue microenvironment and reprogram macrophage function in a manner reminiscent of tumor biology." (PMID 42222744, 2026). "KRAS, NRAS, BRAF, and PIK3CA mutations occur at different frequencies in CRC and exert distinct effects on tumor biology, including the composition and functional properties of the TME, particularly its immune component." (PMID 41596586, 2026). "In this study, we further investigated the requirement of PIK3CA for tumor growth both in vitro and in vivo." (PMID 41892297, 2026). "In this study, we further investigated the requirement for PIK3CA for tumor growth both in vitro and in vivo." (PMID 41676515, 2026). "P03 also has mutations in MTOR and ELF3, while P04 has mutations in FGFR1, and P05 has mutations in PIK3CA and NTRK1–genes involved in tumor growth and survival." (PMID 41012124, 2025).
tumor (continued). "Toward this end, we investigated MGST1 function in LSCC cells and observed that silencing MGST1 significantly inhibited tumor cell proliferation, migration, and invasion, likely through downstream suppression of PIK3CA, NF-KB, β-catenin and GSK3β." (PMID 40778224, 2025). "PTCs harboring BRAFV600E mutations often display concurrent mutations in PIK3CA and AKT1; mutations in the SWI/SNF complex have also been identified in in vivo models coexisting with BRAFV600E mutations, jointly promoting tumor progression." (PMID 41462994, 2025). "Preclinical and early clinical studies demonstrate that dual inhibition—such as combining MEK and PI3K inhibitors—can induce synergistic apoptosis and tumor regression, particularly in tumors harboring KRAS, BRAF, or PIK3CA mutations." (PMID 40943615, 2025). "The PI3K-Akt signaling pathway is critical in the regulation of tumor cell growth and metabolism, and PIK3CA, an isoform of PI3K, has been demonstrated to be amplified in a variety of cancer cells, such as gastric, thyroid, breast, oesophageal, and LUAD." (PMID 41154714, 2025). "addressed the heterogeneity of the mutations predicting the resistance to anti‐EGFR treatment (KRAS, NRAS, BRAF and/or PIK3CA) in the primary CRC tumours in the context of the proportion of neoplastic cells." (PMID 40302146, 2025). "ER+ BC tumours with alterations in PIK3CA are sensitive to PI3Kαi and AKTi, while those with alterations in PIK3CA and PTEN are sensitive to AKTi, with enhanced therapeutic benefit when they are combined with inhibitors of ER signalling." (PMID 40263319, 2025). "In our study, PIK3CA and AKT1 mutations were associated with smaller tumor size and more uniform texture, although these associations did not meet the strict criteria for significance after Bonferroni correction." (PMID 40002579, 2025). "Machine learning (ML) models can predict resistance to endocrine therapies or HER2-targeted agents based on genomic alterations (e.g., BRCA1/2, PIK3CA) and tumor microenvironmental factors." (PMID 40941035, 2025). "Next generation sequencing of the tumor at baseline showed microsatellite instability high (loss of MLH1 and PMS2 and TMB 15, ARID1A G801FS*32, KRAS Q6H, PIK3CA N1044K, PTEN R130G, SMARCA4 P109FS*194 and SMARCA4 P316FS*10 mutations)." (PMID 40382524, 2025). "We employed targeted next-generation sequencing to analyze seven actionable driver genes - EGFR, KRAS, NRAS, BRAF, ALK, ROS1, and PIK3CA - in formalin-fixed, paraffin-embedded tumor specimens from Vietnamese NSCLC patients." (PMID 40502411, 2025). "Loss of PTEN can limit the activity of drugs that target p110α particularly in PIK3CA altered tumours, and treatment with PI3Kβ inhibitors overcomes PTEN protein loss mediated resistance." (PMID 40263319, 2025). "The activation of this pathway often results from mutations or amplifications in PIK3CA (the gene encoding the catalytic subunit of PI3K) or the loss of function of PTEN, a tumor suppressor that negatively regulates PI3K signaling." (PMID 40427514, 2025).